ATG16L1 (autophagy related 16 like 1)
Diseases named in the same sentence as ATG16L1 in open-access papers (continued):
Sharing a sentence is not in itself a finding about the gene and the disease.
Sepsis (7 papers, 2014 to 2025). Sepsis is defined as life-threatening organ dysfunction caused by a dysregulated host response to infection. "A stable sepsis diagnostic model integrating the two most important ferroptosis markers, ATG16L1 and SRC, was constructed using a variety of machine learning models." (PMID 38780016, 2024). "Beyond cellular necroptosis, myeloid-specific loss of Atg16l1 sensitizes mice to LPS-mediated sepsis in vivo." (PMID 31287416, 2019). "The ATG16L1 hypomorphic mouse, with decreased autophagy activity, was clearly associated with predisposition to lethality in pneumonia and sepsis models of Staphylococcus aureus infection." (PMID 28839236, 2017). "We then explored the possible associations of these genetic polymorphisms of ATG5 and ATG16L1 with the occurrence of sepsis." (PMID 28839236, 2017). "In this present study, five polymorphisms of ATG5/ATG16L1 were investigated for the possible risk on sepsis in a Chinese Han population." (PMID 28839236, 2017). "The genotype/allele frequency distributions of ATG5 and ATG16L1 polymorphisms in two subgroups stratified by 28-day mortality of sepsis patients were further evaluated." (PMID 28839236, 2017). "Since Zbp1 deletion enhanced TRIF-mediated necroptosis in Atg16l1-cKO BMDMs ex vivo, we asked whether loss of Atg16l1 and Zbp1 in myeloid cells would further exacerbate LPS-mediated sepsis." (PMID 31287416, 2019). "Combined loss of myeloid-specific Atg16l1 and Zbp1 accelerates LPS-mediated sepsis in mice." (PMID 31287416, 2019). "These lines of evidence demonstrate that ATG5 and ATG16L1, which have been implicated in autophagy initiation and regulation, play a significant role in the pathogenic mechanism underlying the development of sepsis." (PMID 28839236, 2017). "In this hospital-based case-control study, we investigate the clinical relevance of three ATG5 polymorphisms (rs510432, rs506027 and rs548234) and two ATG16L1 polymorphisms (rs10210302 and rs2241880) for susceptibility to and progression of sepsis in a Chinese Han population." (PMID 28839236, 2017). "To evaluate whether three ATG5 polymorphisms (rs510432, rs506027 and rs548234) and two ATG16L1 polymorphisms (rs10210302 and rs2241880) were associated with sepsis progression, we separated the cases into mild sepsis, severe sepsis and septic shock subgroups on the basis of sepsis severity." (PMID 28839236, 2017). "Second, in this study only five ATG5 and ATG16L1 genetic polymorphisms implicated in the susceptibility and progression of sepsis were examined, whereas other polymorphisms of ATG5/ATG16L1 and other autophagy-related genes that may be associated with sepsis remained to be identified." (PMID 28839236, 2017). "In summary, ATG16L1 overexpression provides significant benefits against sepsis‐induced lung injury." (PMID 40211890, 2025). "In summary, this study revealed that ATG16L1 regulates macrophage NLRP3 activation during sepsis and interacts with alveolar epithelial cells to form a positive feedback activation loop during sepsis‐induced lung injury." (PMID 40211890, 2025). "Therefore, ATG16L1 may be a potential diagnostic and therapeutic target for sepsis." (PMID 38780016, 2024). "Unexpectedly, combined deletion of Atg16l1 and Zbp1 accelerated LPS-mediated necroptosis and sepsis in mice." (PMID 31287416, 2019). "Our results showed that ATG5 and ATG16L1 expression levels in sepsis patients were significantly reduced relative to healthy controls, and that it decreased with the aggravation of sepsis which was consistent with these previous studies." (PMID 28839236, 2017). "A comparative analysis was performed with respect to the mRNA expression of ATG5 and ATG16L1 in the PBMCs of 80 sepsis cases and 80 controls." (PMID 28839236, 2017). "Polymorphism of autophagy-related genes (ATG16L1 and IRGM) was associated with severity and mortality of sepsis." (PMID 25625512, 2015).
Sepsis (continued). "However, the specific role of ATG16L1 in macrophages and its mechanisms of action in sepsis‐induced lung injury remains poorly understood." (PMID 40211890, 2025). "Furthermore, immunofluorescence co‐localisation analysis confirmed that ATG16L1 was upregulated in lung macrophages during sepsis." (PMID 40211890, 2025). "ATG16L1 expression was measured in lung from mice with sepsis." (PMID 40211890, 2025). "In vivo experiments in a rat sepsis model validated the differential expression of ATG16L1 and SRC." (PMID 38780016, 2024). "Likewise, this study observed that a combination of 1,25D3 and butyrate enhanced the autophagy gene ATG16L1 but suppressed proinflammatory IL-1β mRNA expression in chemotherapy-receiving mice complicated with gut-derived P. aeruginosa sepsis." (PMID 38790988, 2024). "All samples were sequenced and genotyped successfully and no deviations from Hardy-Weinberge quilibrium were observed for these ATG5 and ATG16L1 polymorphisms in sepsis and control groups (all P > 0.05, data not shown)." (PMID 28839236, 2017). "Our findings reveal a new role for ATG16L1 in regulating macrophage NLRP3 feedback activation during sepsis, suggesting it as a potential therapeutic target for treating sepsis‐induced ALI." (PMID 40211890, 2025). "In the rat cecal ligation puncture sepsis model, in vivo experiments verified the involvement of ATG16L1 and SRC in the early sepsis process." (PMID 38780016, 2024). "Both Nissl and TUNEL staining indicated that overexpression of ATG16L1 and SRC significantly promoted the recovery of neuronal activity after sepsis and inhibited apoptosis in myocardial and lung tissues of septic rats." (PMID 38780016, 2024). "In addition, considering the dual biological functions of the two ferroptosis characteristic genes, ATG16L1 and SRC, it is necessary to elucidate their exact role and specific regulatory mechanisms in sepsis through in vivo and in vitro studies." (PMID 38780016, 2024). "It has been reported that mice lacking ATG16L1 had accelerated LPS (Lipopolysaccharide) ‐mediated necroptosis and sepsis." (PMID 38780016, 2024). "After regulating the overexpression of specific targets, it could significantly alleviate the degree of organ damage in septic rats, further indicating that ATG16L1 and SRC function early in sepsis, and the increased expression was able to relieve sepsis." (PMID 38780016, 2024). "The expression levels of ATG5 and ATG16L1 in the 28-day non-surviving patients with sepsis were significantly decreased compared to the 28-day surviving patients (P < 0.01)." (PMID 28839236, 2017). "In addition, mice lacking ATG16L1 in bone marrow cells are more likely to die of LPS‐mediated sepsis." (PMID 38780016, 2024). "Our results showed that the ATG5 and ATG16L1 expression levels in the sepsis cases were significantly reduced relative to the controls (P < 0.001), and it is worth nothing that the ATG5 and ATG16L1 mRNA expression levels decreased significantly with the aggravation of sepsis (P < 0.05)." (PMID 28839236, 2017). "However, the regulatory mechanism of ATG16L1 on NLRP3 and its role in sepsis remain unclear." (PMID 40211890, 2025).
autoimmune disease (6 papers, 2015 to 2025). A disorder resulting from loss of function or tissue destruction of an organ or multiple organs, arising from humoral or cellular immune responses of the individual to their own tissue constituents. "We demonstrate that miR-142-3p downregulates ATG16L1 mRNA and production of ATG16L1, that has been linked to autoimmune diseases." (PMID 29459719, 2018). "ATG16L1 is crucial in regulating inflammatory responses and autoimmune diseases by suppressing IL-1β signaling, and its inhibition by EHEC may trigger host inflammatory reactions." (PMID 41522448, 2025). "In some other autoimmune diseases, ATG16L1 was also found upregulated in dendritic cells." (PMID 25883416, 2015).
intestinal inflammation (6 papers, 2017 to 2023). "Atg16L1−/− mice spontaneously developed intestinal inflammation, due to the increased ratio of pro-inflammatory cytokines." (PMID 32659925, 2020). "Conversely, other autophagy-related genes (ATG16L1 and IRGM) seemed to play important roles for autophagy in maintaining intestinal homeostasis, and the overall dysfunction of autophagy resulted in being a major risk factor for the onset of chronic intestinal inflammation." (PMID 28208686, 2017).
enteritis (5 papers, 2020 to 2026). Inflammation of the small intestine. "By contrast, the prototypical TLR2 ligand Pam2CSK4 was still able to induce an inflammatory response from Atg16l1-deficient IECs, and Pam2CSK4 instigated enteritis in our model." (PMID 41382985, 2026). "Moreover, CD patients that have Paneth cell ER stress due to ATG16L1 gene mutations are colonized by enteroinvasive E. coli which induce enteritis in higher rates." (PMID 32345659, 2020). "We assessed the impact of Atg16l1-deficiency on PUFA-induced CXCL1 (C-X-C motif chemokine ligand 1) expression, as this chemokine (besides CXCL2) was potently induced in our model system and contributes to enteritis in Gpx4+/-IEC mice." (PMID 41382985, 2026). "We further studied how Atg16l1 governed PUFA-induced chemokine production in Gpx4-deficient IECs and whether such a mechanism is relevant for PUFA-induced enteritis." (PMID 41382985, 2026). "Moreover, Pam2CSK4 gavage into Gpx4+/-IEC;atg16l1-/-IEC mice (for 7 consecutive days in the last week of exposure to a PUFA-enriched western diet for 3 months) was sufficient to instigate enteritis in this model." (PMID 41382985, 2026). "Notably, Gpx4+/-IEC;atg16l1-/-IEC double mutant mice were protected against PUFA-induced enteritis and against systemic inflammation when compared to Gpx4+/-IEC mice." (PMID 41382985, 2026). "In addition, we observed increased small intestinal enteritis score in Atg16l1/Xbp1/Rnaseh2bΔIEC, compared to Xbp1/Rnaseh2bΔIEC." (PMID 41057521, 2025). "Bulk RNA sequencing of PUFA-exposed model IECs suggested that ATG16L1 is required for TLR2-mediated stress signaling and enteritis, which we corroborated in reporter cells and mice." (PMID 41382985, 2026). "This study confirmed the effect of DSS on the expression of autophagy-related 16-like 1 (ATG16L1) and X-box binding protein-1 (XBP1), genes used to evaluate the innate immune system, including DEFA5, in enteritis models." (PMID 39329151, 2024). "Although epithelial cell death is not phenotypically characterizing enteritis in intestinal-epithelial-specific Gpx4-deficient mice with or without PUFA exposure, we found that ATG16L1-mediated autophagy is required for the inflammatory phenotype, as similarly reported for ferroptosis." (PMID 41382985, 2026).
fatty liver (5 papers, 2017 to 2025). "Vitamin D has also been found to improve hepatic steatosis by enhancing autophagy via the upregulation of autophagy-related 16-like 1 (ATG16L1)." (PMID 38732118, 2024).
prostate carcinoma (5 papers, 2015 to 2024). A carcinoma that arises from epithelial cells of the prostate gland. "The OS-related prognostic model was constructed based on the five ARGs (FAM215A, FDD, MYC, RHEB, and ATG16L1) and significantly stratified prostate cancer patients into high- and low-risk groups in terms of OS (HR = 6.391, 95% CI = 1.581– 25.840, P < 0.001)." (PMID 32264916, 2020). "The association of the replicated marker, ATG16L1 rs78835907, with prostate cancer progression from localized to ADT-treated patients reinforces the validity of our finding." (PMID 26365175, 2015). "ATG16L1 rs78835907 was consistently associated with a reduced risk of disease progression in patients with localized and advanced prostate cancer." (PMID 26365175, 2015). "Only 1 variant, ATG16L1 rs78835907, showed significant association with disease progression of advanced prostate cancer after adjustment for known clinical factors (P = 0.014)." (PMID 26365175, 2015). "Besides, some of the mutations in ATG5 genes found in the DU145 prostate cancer cell line may interfere its functions, such as binding with ATG16L1 and ATG5-ATG12 conjugation." (PMID 33926066, 2021). "There was a trend toward decreased ATG16L1 gene expression with more aggressive forms of prostate cancer (P ≤ 0.088)." (PMID 26365175, 2015). "We have also presented additional evidence for a role of ATG16L1 in prostate cancer, as downregulated ATG16L1 gene expression in tumors was correlated with poorer clinical outcomes, and thereby strengthening the evidence of this genotype-phenotype association." (PMID 26365175, 2015). "Previous research analyzed the relationship between genetic variants of the autophagy pathway and clinical outcomes in 458 prostate cancer patients, which indicated that high expression of ATG16L1 was correlated with lower tumor aggressiveness and favorable prognosis." (PMID 32264916, 2020). "Taken together, our data suggest that rs78835907 G allele alters the binding affinity of HDAC2 to the DNA, which in turn reduces the expression of ATG16L1, consequently contributing to the more aggressive phenotype and poorer clinical outcome in prostate cancer." (PMID 26365175, 2015). "Three SNPs, ATG16L1 rs78835907, ATG16L1 rs13021297, and MAP1LC3B rs8044820, remained significant, and were selected to replicate findings in advanced prostate cancer cohort." (PMID 26365175, 2015). "A potential role of decreased autophagy in promoting prostate cancer progression has been suggested through correlations between low prostate tumour expression of the core ATG genes FIP200, ATG16L1, or GABARAPL1 and poor prognosis in clinical prostate cancer cohorts." (PMID 38910881, 2024).
diabetes (4 papers, 2018 to 2023). "Our findings on the association between genetic variants in AMBRA1, ATG13 and ATG16L1 and proinsulin levels are in agreement with previous evidence reporting autophagy deficiency as an important determinant in the pathogenesis of insulin resistance and diabetes." (PMID 30908504, 2019). "Human pancreatic islets highly express intracellular C3, and C3 binds autophagy-related protein 16-1 (ATG16L1), thus regulating autophagy and contributing to β cell survival in human islet inflammation and diabetes." (PMID 36969185, 2023).
laryngeal carcinoma (4 papers, 2017 to 2025). Carcinoma that arises from the laryngeal epithelium. "We found an association between the variant in ATG10 rs1864183 and a higher susceptibility to develop laryngeal cancer, ATG2B rs3759601 and pharyngeal cancer and ATG16L1 rs2241880 and oral carcinoma." (PMID 28761177, 2017).
melanoma (4 papers, 2016 to 2021). A malignant, usually aggressive tumor composed of atypical, neoplastic melanocytes. "Given the similar levels of ATG16L1 across all the different stages of melanoma progression, the expression of ATG16L1 was unrelated to the outcome of patients." (PMID 34458153, 2021). "While it is unknown if ATG16L1 likewise possesses pro-apoptotic activity, hemizygous ATG5 deletions and ATG5 mRNA downregulation in human melanomas are associated with metastasis and poor patient survival." (PMID 31636955, 2019). "The expression levels of the autophagy proteins ATG5, ATG7, ATG16L1, and two autophagic markers, LC3B and p62, were assessed in melanoma patients by immunohistochemistry." (PMID 34458153, 2021).
Parkinson disease (4 papers, 2023 to 2025). A progressive degenerative disorder of the central nervous system characterized by loss of dopamine producing neurons in the substantia nigra and the presence of Lewy bodies in the substantia nigra and locus coeruleus. "Two significant gene clusters (clusters 7 and 73) included genes previously associated with Parkinsonism (FIG4 and VAC14) and IBD (IFNAR1, IL6ST, ATG16L1, and NOD2)." (PMID 38741190, 2024). "In the substantia nigra of a Parkinson’s disease (PD) rat model, p62, Atg5, Atg12, LC3, and Atg16l1 were expressed, while Atg10 was not expressed." (PMID 36598250, 2023).
systemic lupus erythematosus (4 papers, 2013 to 2024). An autoimmune multi-organ disease typically associated with vasculopathy and autoantibody production. "For instance, in chronic autoimmune skin diseases, psoriasis has been reported that could be associated with SNPs in the ATG16L1 gene, and systemic lupus erythematosus (SLE) could be associated with a genetic variant within or near ATG5 gene." (PMID 27941683, 2016).
ZIKV infection (4 papers, 2019 to 2020). "ZIKV infection induces autophagy in vivo, whereas loss of Atg16l1 expression impairs the intrauterine transmission of ZIKV." (PMID 32410874, 2020). "Conversely, inhibition of autophagy through a knockout model of a key autophagy gene, atg16l1, important for autophagosome formation inhibited placental ZIKV infection and vertical transmission in a mouse model." (PMID 31451049, 2019).
COVID-19 (3 papers, 2023 to 2024). A disease caused by infection with severe acute respiratory syndrome coronavirus 2. "Additionally, the distribution of the haplotypes of NLRP3, NLRC4, NLRP1, CARD8, CASP1, IL1B, and ATG16L1, with a frequency greater than 5% in HC, were similar between COVID-19 patients with mild, moderate, severe, and critical infection, and HC." (PMID 38612539, 2024). "Furthermore, ATG16L1 rs2241880 and AGT5 rs506027 polymorphisms appear to be relevant in COVID-19, prompting deeper investigations." (PMID 38136993, 2023).
glioblastoma (3 papers, 2020 to 2022). The most malignant astrocytic tumor (WHO grade IV). "Here, we aimed to assess the potential association between several candidate polymorphisms in autophagy genes (ATG2B rs3759601, ATG16L1 rs2241880, ATG10 rs1864183, ATG5 rs2245214, NOD2 rs2066844 and rs2066845) and glioblastoma susceptibility." (PMID 35123435, 2022). "In this study, we have analyzed common polymorphisms in genes involved in autophagy (ATG2B rs3759601, ATG16L1 rs2241880, ATG10 rs1864183, ATG5 rs2245214, NOD2 rs2066844 and rs2066845) in order to evaluate their role in the susceptibility to suffer glioblastoma." (PMID 35123435, 2022). "In the current study, we could not find any correlation between ATG16L1 rs2241880 distribution and the susceptibility to develop glioblastoma." (PMID 35123435, 2022).
Insulin resistance (3 papers, 2019 to 2025). Increased resistance towards insulin, that is, diminished effectiveness of insulin in reducing blood glucose levels. "Similar to findings obtained in 3xTg-AD mice, in the presence of insulin resistance, Atg16L1, Atg16L2, and GabarapL1 expression levels were significantly increased." (PMID 36901549, 2023). "Significantly elevated expression of Atg16L1, Atg16L2, and GabarapL1 was also observed in H4Swe cell cultures, in the presence of insulin resistance." (PMID 36901549, 2023). "Similar to findings in 3xTg-AD mice, we found that Atg16L1, Atg16L2, and GabarapL1 were significantly elevated in insulin resistance conditions." (PMID 36901549, 2023). "Gene expression analysis confirmed that Atg16L1 was significantly increased in cultures from transgenic mice when insulin resistance was induced." (PMID 36901549, 2023). "Interestingly, the depletion of ATG3 and ATG16L1 in adipose tissue has been shown to result in systemic insulin resistance and increased hepatic gluconeogenesis, both of which are characteristic features of T2DM." (PMID 41439967, 2025). "Furthermore, mice subjected to a high-fat diet exhibited reduced levels of Atg16L1 and IRS1 in epididymal white adipose tissue, suggesting that insulin resistance may result from diminished expression of Atg16L1, leading to the subsequent degradation of IRS1." (PMID 41439967, 2025). "Gene expression analysis confirmed that Atg16L1 was significantly increased in cultures from transgenic mice when insulin resistance was induced, whereas no other difference was detected in the other genes analysed." (PMID 36901549, 2023).
Listeria infection (3 papers, 2012 to 2025). "The WD domain of ATG16L1 maintains membrane repair during Listeria infection independently of conventional autophagy." (PMID 33586810, 2021).